GRP (gastrin releasing peptide)
Description:
Stimulates the release of gastrin and other gastrointestinal hormones (By similarity). Contributes to the perception of prurient stimuli and to the transmission of itch signals in the spinal cord that promote scratching behavior (By similarity). Contributes primarily to nonhistaminergic itch sensation (By similarity). In one study, shown to act in the amygdala as part of an inhibitory network which inhibits memory specifically related to learned fear (By similarity). In another study, shown to act on vasoactive intestinal peptide (VIP)-expressing cells in the auditory cortex, most likely via extrasynaptic diffusion from local and long-range sources, to mediate disinhibition of glutamatergic cells via VIP cell-specific GRPR signaling which leads to enhanced auditory fear memories (By similarity). Contributes to the regulation of food intake (By similarity). Inhibits voltage-gated sodium channels but enhances voltage-gated potassium channels in hippocampal neurons (By similarity). Induces sighing by acting directly on the pre-Botzinger complex, a cluster of several thousand neurons in the ventrolateral medulla responsible for inspiration during respiratory activity (By similarity). [Neuromedin-C]: Induces an itch response through activation of receptors present on mast cells, triggering mast cell degranulation.
Synonyms: BN; GRP-10; preproGRP; proGRP
Tractability: Small molecule: a structure with a bound ligand is known. Antibody: UniProt places it where antibodies can reach, with high confidence; its Gene Ontology location is reachable by antibodies, with high confidence; UniProt predicts a signal peptide or a membrane-spanning region. PROTAC: ubiquitination databases record sites on it.
Gene: Protein-coding gene on chromosome 18 (59,220,158 to 59,230,774, forward strand). Ensembl gene ENSG00000134443.
Subcellular location: Secreted; Cytoplasmic vesicle, secretory vesicle lumen; Cell projection, neuron projection
Pathways (Reactome):
Signal Transduction: G alpha (q) signalling events; Peptide ligand-binding receptors
Metabolism of proteins: Synthesis, secretion, and inactivation of Glucagon-like Peptide-1 (GLP-1)
Gene Ontology:
Molecular function: neuropeptide hormone activity; protein binding; signaling receptor binding
Biological process: neuropeptide signaling pathway; mast cell degranulation; negative regulation of transmission of nerve impulse; positive regulation of behavioral fear response; positive regulation of peptide hormone secretion; positive regulation of phospholipase C-activating G protein-coupled receptor signaling pathway; positive regulation of respiratory gaseous exchange; signal transduction; psychomotor behavior; response to external biotic stimulus; social behavior
Cellular component: extracellular region; neuron projection; secretory granule lumen; cytoplasmic vesicle
Genetic constraint (gnomAD): Loss-of-function variants: 11 observed, 9.49 expected, observed/expected ratio (o/e) 1.16, 90% interval 0.73 to 1.8. That is too few expected variants to judge how well the gene tolerates losing a copy. Missense variants: 171 observed, 139.19 expected, observed/expected ratio (o/e) 1.23, 90% interval 1.08 to 1.39. Synonymous variants: 75 observed, 58.53 expected, observed/expected ratio (o/e) 1.28, 90% interval 1.06 to 1.55.
Homologues: Orthologues: macaque GRP (94% identical), chimpanzee GRP (84% identical), dog GRP (71% identical), pig GRP (71% identical), guinea pig GRP (61% identical), rat Grp (59% identical), mouse Grp (57% identical), rabbit GRP (55% identical), tropical clawed frog grp (29% identical). Paralogues in human: NMB (22% identical).
Diseases named in the same sentence as GRP in open-access papers:
GRP is named in the same sentence as 133 diseases in open-access papers, as found by Europe PMC text mining. Sharing a sentence is not in itself a finding about the gene and the disease. The quoted sentences say what the papers report.
lung carcinoma (66 papers, 2010 to 2026). "Currently, the widely used diagnostic markers for lung cancer are pro-gastrin-releasing peptide (ProGRP), neuron-specific enolase (NSE), carcinoembryonic antigen (CEA), and cytokeratin 19 fragment (CYFRA21-1)." (PMID 30940109, 2019). "Notably, Pro-Gastrin Releasing Peptide(ProGRP)and inflammatory markers were independently associated with the risk of lung cancer (P < 0.05)." (PMID 41943036, 2026). "However, it has been suggested that the sensitivity and specificity of NSE are inferior to those of pro-gastrin-releasing peptide (ProGRP), indicating that its diagnostic value for pulmonary nodules or lung cancer remains limited." (PMID 41536835, 2025). "Meanwhile, combined monitoring of tumor markers such as serum CEA, NSE, CYFRA21‐1, and Pro‐GRP is important in the prognostic assessment of lung cancer patients." (PMID 40488279, 2025). "Five tumor markers, namely CEA, CY211, CA125, NSE, and GRP, exhibited significance in distinguishing healthy patients from those with lung cancer." (PMID 38549716, 2024). "Our investigation revealed studies that used binary logistic regression to demonstrate the value of CEA, CA125, pro-GRP, and age in distinguishing between healthy patients and those with lung cancer." (PMID 38549716, 2024). "In a comparison between the healthy population and patients with lung cancer, CEA, CA125, and CY211 had good diagnostic effects in lung cancer screening (AUC > 0.7), whereas NSE and GRP had limited diagnostic value for pulmonary cancer (AUC < 0.7)." (PMID 38549716, 2024). "The five tumor markers—CEA, CA125, CY211, NSE, GRP—show promising results in screening healthy individuals and patients with lung cancer." (PMID 38549716, 2024). "Binary logistic regression revealed that in healthy participants, CEA (P <0.001), CA125 (P <0.001), GRP (P=0.001), and age (P=0.004) were significant factors affecting lung cancer screening." (PMID 38549716, 2024). "There were significant differences in serum Cyfra21-1 (P = 0.003), CEA (P = 0.008), NSE (P = 0.036), and Pro-GRP (P = 0.006) levels among the benign lung disease and lung cancer." (PMID 37476198, 2023). "The AUCs of 4MP and 7MP (NSE, SCC, Pro-GRP, and 4MP) in distinguishing benign lung disease and lung cancer were 0.808 and 0.832, respectively." (PMID 37476198, 2023). "It means that the NSE, SCC, and Pro-GRP can be used as resultful auxiliary detection items of the 4MP, which can effectively help the 4MP to complete the stratification of different lung cancer subtypes." (PMID 37476198, 2023). "The most significant contribution to the identification of advanced lung cancer and benign lung diseases is Pro-GRP, which is abnormally elevated in serum levels in advanced cancer." (PMID 37476198, 2023). "This study also discussed the auxiliary role of conventional lung cancer diagnostic markers CEA, NSE, and Pro-GRP for the 4MP in early diagnosis of lung cancer." (PMID 37476198, 2023). "GRPR and GRP are involved in an autocrine stimulation loop in lung cancer and HNSCC, and GRPR expression has been shown to be positively regulated by GRP." (PMID 22296774, 2012). "Similar to prostate cancers, lung cancers express GRP and GRPR where they promote tumor progression and metastatic spread through autocrine and paracrine mechanisms." (PMID 21745389, 2011). "Compared with lung benign diseases group and health control group, the positive rates and levels of TPS, CEA and Pro-GRP in patients with lung cancer were higher, with statistically signifcant difference." (PMID 20677649, 2010). "However, only CEA, NSE, and GRP levels were effective in distinguishing patients with benign lung lesions from those with lung cancer." (PMID 38549716, 2024). "However, only CEA, NSE, and GRP effectively differentiate patients with benign lung lesions from those with lung cancer." (PMID 38549716, 2024). "CEA, CY211, CA125, NSE, and GRP are relevant tumor markers for lung cancer." (PMID 38549716, 2024).
lung carcinoma (continued). "Among them, the carcinoembryonic antigen (CEA), cytokeratin-19-fragment (CYFRA21-1), pro-gastrin-releasing peptide (ProGRP), and neuron-specific enolase (NSE) are specific tumour markers for the differential diagnosis of lung cancer and have a high diagnostic sensitivity." (PMID 38099241, 2023). "As we know, tumor markers have been widely used in the detection of lung cancer in recent years, such as progastrin-releasing peptide (ProGRP), vascular endothelial growth factor (VEGF), carcinoembryonic antigen (CEA), cytokeratin 19 fragment (CYFRA21-1) and neuronspecific enolase (NSE)." (PMID 32445550, 2020). "Currently, serum biomarkers such as cytokeratin 19 fragment (CYFRA21-1), pro-gastrin releasing peptide (ProGRP), carcinoembryonic antigen (CEA), neuron-specific enolase (NSE), and squamous cell carcinoma-associated antigen (SCCA) have shown potential clinical utility for diagnosing lung cancer." (PMID 39888565, 2025). "Commonly used blood-based biomarkers for lung cancer diagnosis, such as carcinoembryonic antigen (CEA), carbohydrate antigen 19-9 (CA19-9), neuron-specific enolase (NSE), and pro-gastrin-releasing peptide (ProGRP), have been extensively applied." (PMID 40708824, 2025). "Presently recommended biomarkers for lung cancer include carcinoembryonic antigen (CEA), progastrin‐releasing peptide (ProGRP), cytokeratin 19 fragment (Cyfra21‐1), neuron‐specific enolase (NSE), and squamous cell carcinoma antigen (SCC)." (PMID 38742362, 2024). "The primary lung cancer markers recommended in the 2015 lung cancer guidelines include CEA, NSE, CYFRA21-1, pro-GRP, and SCC." (PMID 38549716, 2024). "The tumor-associated antigens (TAAs) including CEA, NSE, CA125, SCC, CA15-3, pro-GRP, and CYFRA21-1 are widely used blood-based biomarkers that help to diagnose lung cancer." (PMID 36874112, 2023). "The best-known biochemical markers used in the diagnosis of lung cancer are carcinoembryonic antigen (CEA), cytokeratin 19 fragment (CYFRA21-1), and pro-gastrin-releasing peptide (ProGRP), the use of which is becoming more widespread." (PMID 37444393, 2023). "Lung cancer-related serum markers commonly include carcinoembryonic antigen (CEA), neuron-specific enolase (NSE), cytokeratin fragment 19 (CYFRA21-1), Pro-gastrin-releasing peptide (ProGRP), squamous cell carcinoma antigen (SCCA)." (PMID 36568217, 2022). "Tumor markers for lung cancer such as CEA, Cyfra21-1, NSE, and pro-GRP, due to their low sensitivity and specificity, have limited clinical application value." (PMID 36046366, 2022). "Tumor markers commonly used for lung cancer include carcinoembryonic antigen (CEA), cytokeratin 19 (Cyfra21-1), neuron-specific enolase (NSE), gastrin-releasing peptide precursor (pro-GRP), and squamous cell carcinoma antigens (SCAA)." (PMID 36046366, 2022). "This gastrin-releasing peptide (GRP) binds specifically to GRP receptors overexpressed in breast, prostate, and lung cancers." (PMID 34832857, 2021). "Traditional clinical blood biomarkers of lung cancer include; neuron-specific enolase (NSE), progastrin-releasing peptide (pro-GRP), carcinoembryonic antigen (CEA), CYFRA 21-1, cancer antigen 15 (CA125) and squamous cell carcinoma antigen (SCC)." (PMID 34295810, 2021). "A panel of biomarkers (in particular, CYFRA 21-1 (cytokeratins), EPCAM (epithelial cell adhesion molecule), ProGRP (pro-gastrin-releasing peptide), CEACAM (carcinoembryonic antigen), and others are used for screening various malignancies including lung cancer." (PMID 29137182, 2017). "Gastrin-releasing peptide (GRP) was first isolated from the stomach of pigs in 1978 and has since been found to be distributed in various organs and tissues, including the fetal lung and lung cancer, with good sensitivity and specificity." (PMID 38549716, 2024). "Conversely, CEA, NSE, and GRP demonstrated significance in discriminating benign lung lesions from lung cancer, whereas CA125 and CY211 did not." (PMID 38549716, 2024).
lung carcinoma (continued). "Traditional lung cancer biomarkers NSE, SCC, and Pro-GRP can significantly improve the performance of 4MP in the differentiation of LADC, SQCLC, and SCLC, which is expected to contribute to the accurate diagnosis and personalized treatment of patients with lung cancer." (PMID 37476198, 2023). "The two groups were compared in terms of baseline data and lung cancer biomarkers, including carcinoembryonic antigen (CEA), neuron-specific enolase (NSE), cytokeratin 19 fragment 21–1 (CYFRA 21–1), squamous cell carcinoma antigen (SCCA), and pro-gastrin-releasing peptide (ProGRP)." (PMID 41536835, 2025). "Thus, it can be concluded that the detection of serum NSE, SCC, and Pro-GRP levels was not apparent for the auxiliary diagnosis of 4MP in distinguishing benign lung disease and lung cancer." (PMID 37476198, 2023). "Moreover, serum biomarker examination for lung cancer were abnormal as follows: carcinoembryonic antigen (CEA) at 13.74 ng/mL, cytokeratin 19 fragment (CYFRA21-1) at 6.82 ng/mL, neuron-specific enolase (NSE) at 25.49 ng/mL, and progastrin-releasing peptide precursor (ProGRP) at 89.35 pg/mL." (PMID 39850892, 2024). "Additionally, serum biomarkers of lung cancer were abnormal as follows: carcinoembryonic antigen (CEA) at 13.74 ng/mL, cytokeratin 19 fragment (CYFRA21-1) at 6.82 ng/mL, neuron-specific enolase (NSE) at 25.49 ng/mL, and progastrin-releasing peptide precursor (ProGRP) at 89.35 pg/mL." (PMID 39850892, 2024). "CEA, CA125, and CY211 were effective in differentiating healthy participants from those with lung cancer (AUC > 0.7), whereas NSE and GRP were not (AUC < 0.7)." (PMID 38549716, 2024). "A study revealed that RA can elicit gastrin-releasing peptide (GRP), a growth factor that can act as a tumor promoter, by activating intact retinoid signaling, implying that retinoids interestingly may enhance rather than decreasing the risk of lung cancer in some people." (PMID 35631448, 2022). "In addition, refuinement lung cancer related serum tumor markers showed negative, including CEA, Pro GRP, CYFRA21-1, CA125, NSE, and SCC." (PMID 41001035, 2025).
small cell lung carcinoma (39 papers, 1994 to 2026). Small cell lung cancer (SCLC) is a highly aggressive malignant neoplasm, accounting for 10-15% of lung cancer cases, characterized byrapid growth, and early metastasis. "Among neuroendocrine tumors, plasma progastrin-releasing peptide (ProGRP) (upper limit of the normal range: 81 pg/mL) is routinely used as a specific tumor marker for small-cell lung cancer in clinical practice." (PMID 40151714, 2025). "The model protein used for this purpose was progastrin releasing peptide (ProGRP), a validated low abundant biomarker for Small Cell Lung Cancer with reference values in serum in the pg mL−1 range." (PMID 35702551, 2019). "Compared with NSE, progastrin-releasing peptide (ProGRP) is more sensitive and specific in the detection of small cell lung cancer; thus, it has been used to complement NSE in the diagnosis and monitoring of SCLC, especially in its early stages." (PMID 30781735, 2019). "Gastrin releasing peptide (GRP) is an autocrine growth factor in small cell lung cancer, which has very poor patient outcomes." (PMID 31921534, 2019). "Serum sialyl Lewis X antigen level increased when the adenocarcinoma component was dominant, whereas plasma pro-gastrin-releasing peptide level increased when the small-cell lung cancer component became dominant." (PMID 24195468, 2013). "The low abundant protein progastrin-releasing peptide (ProGRP), a tumor marker for small cell lung cancer (SCLC), was used to evaluate the on-line system." (PMID 24336509, 2013). "In a recent study, a combination of common chemotherapy and immunotherapy targeting BN/GRP-receptor with a synthetic BN/GRP antagonist was found to enhance the killing of small-cell lung cancer cells." (PMID 15899028, 2005). "The synergistic effects of L-His-ZIF-8 thus enhanced the ECL of Au NCs by improving both electron transfer and radiative transitions, achieving quantitative detection of pro-gastrin-releasing peptide (Pro-GRP), a tumor marker for the diagnosis of small cell lung cancer." (PMID 41471772, 2025). "Nevertheless, in case of suspicious masses, studies have shown that newer TMs provide improved profiles of sensitivity and specificity for defined malignancies such as progastrin-releasing peptide (ProGRP) for small cell lung cancer and human epididymis protein 4 (HE4) for ovarian cancer." (PMID 28042579, 2016). "Higher concentrations of the small-cell lung cancer (SCLC) serum marker, pro-gastrin-releasing peptide (proGRP), in lung inflammations has been indicated in literature." (PMID 39703761, 2025). "For example, CYFRA21-1 and SCC are more sensitive to lung squamous cell carcinoma, while Pro-GRP and NSE are more sensitive to small cell lung carcinoma." (PMID 37361581, 2023). "Similarly, peptide hormones like gastrin-releasing peptide (GRP) and its more stable precursor pro-GRP, when combined with established markers such as NSE, improve sensitivity in detecting small cell lung cancer (SCLC)." (PMID 41008874, 2025). "A known small cell lung cancer (SCLC) biomarker is a pro-gastrin-releasing peptide (ProGRP), but not for all LNENs, especially for bronchopulmonary carcinoids." (PMID 37444393, 2023). "Small cell lung cancer (SCLC), a neuroendocrine tumor, has high levels of GRP." (PMID 28785244, 2017). "Furthermore, in small cell lung cancer, microbiota richness and diversity were inversely correlated with Eastern Cooperative Oncology Group (ECOG) performance status (p = 0.008, p < 0.001, respectively) and pro-gastrin-releasing peptide (ProGRP) levels (p = 0.065, p = 0.084, respectively)." (PMID 41471248, 2025). "We investigated the effects of our synthetic bombesin/gastrin-releasing peptide (GRP) antagonists and somatostatin analogue RC-160 on the growth of human small-cell lung carcinoma (SCLC) and non-small-cell lung carcinoma (non-SCLC) lines in nude mice." (PMID 7947094, 1994).